IL6 (interleukin 6)
Diseases named in the same sentence as IL6 in open-access papers (continued):
Sharing a sentence is not in itself a finding about the gene and the disease.
rheumatoid arthritis (continued). "Previous studies have investigated the role of SNPs in the IL-6 gene in MS and other autoimmune diseases (e.g., rheumatoid arthritis and erythematous systemic lupus)." (PMID 35627281, 2022). "Interleukin-6 (IL-6) is overproduced in the joints of patients with rheumatoid arthritis, suggesting that IL-6 production is a crucial factor in the pathogenesis of the disease." (PMID 35692576, 2022). "A study on a monoclonal antibody (tocilizumab) to transmembrane and sIL-6Rα showed that tocilizumab was effective in patients with rheumatoid arthritis although tocilizumab increased serum levels of IL-6 and sIL-6Rα." (PMID 35909446, 2022). "Anti-TNFa therapy in patients with rheumatoid arthritis decreased cytokines and acute phase proteins including IL-6, IL-1 receptor antagonist, serum amyloid A, haptoglobin, and fibrinogen." (PMID 35740360, 2022). "IL-6 and the IL-6 receptor (IL-6R) axis contribute to various autoimmune diseases, and their inhibition has shown considerable effects in such cases as rheumatoid arthritis." (PMID 36285981, 2022). "Although fewer synovial macrophages are present in OA than in rheumatoid arthritis, they are crucial for the production of pro-inflammatory cytokines, such as IL-6 and TNF-α11." (PMID 35091584, 2022). "Increased plasma IL-6 levels and association with the IL-6 receptor (IL-6R) risk alleles are reported in connective tissue diseases (CTDs) known to cause pulmonary hypertension, such as rheumatoid arthritis (RA)." (PMID 34588193, 2022). "Overexpression of miR-125b induces the expression of TNF-α, IL-6 and IL-1β in plasma from rheumatoid arthritis patients, showing a strong positive correlation between miR-125b and TNF-α." (PMID 36668754, 2022). "JAKinibs exert proven anti-inflammatory properties in rheumatoid arthritis (RA) thanks to their effects on the plasma levels of pro-inflammatory cytokines as IL-6 and IL-17." (PMID 36556466, 2022). "IL-6 increases rapidly even during infections, inflammation, and trauma, and shows high serum concentrations in rheumatoid arthritis and autoimmune diseases." (PMID 35444966, 2022). "IL-6 correlates with disease activity and joint destruction in rheumatoid arthritis (reviewed in Ref." (PMID 36105611, 2022). "IL-6 is an important inflammatory cytokine, and anti-IL-6 receptor or anti-IL-6 antibodies have been approved for the treatment of inflammatory diseases such as rheumatoid arthritis." (PMID 36050717, 2022). "Activation of angiotensin type II-angiotensin type I receptor further stimulates TNF-α and soluble IL-6 rheumatoid arthritis form." (PMID 35178309, 2022). "TNF-α, IL-1β, and IL-6 are mainly involved in acute inflammation, leading to healing, trigger removal, tissue repair, and some systemic autoimmune diseases such as rheumatoid arthritis." (PMID 36613927, 2022). "In rheumatoid arthritis, it downregulates the PI3K/AKT pathway to modulate the proinflammatory responses of associated macrophages, altering the production of IL-6, IL-8 and TNF-α." (PMID 35562916, 2022). "The role of LRG1 as a pro-inflammatory mediator is more clearly established in the pathogenesis of rheumatoid arthritis (RA), where high levels of Th17 cells and Th17-related cytokines, including TNFα and IL-6, cause severe joint destruction and correlate with poor prognosis." (PMID 35062948, 2022). "YBLI of 8 weeks has significantly reduced the expression of TNF-α and IL-6 genes in rheumatoid arthritis patients." (PMID 36004368, 2022). "In fact, targeting IL-6 has led to important therapeutic approaches for the treatment of rheumatoid arthritis, juvenile idiopathic arthritis and Castleman’s disease." (PMID 35432339, 2022). "It seems like inflammatory genes were not responding as they were intended to like in another similar study, in which 8 weeks of yoga-based lifestyle intervention significantly decreased the TNF-α and IL-6 expression in patients with rheumatoid arthritis." (PMID 36004368, 2022).
rheumatoid arthritis (continued). "Since IL-6 is also important in the pathophysiology of rheumatoid arthritis (RA), tocilizumab, an antibody against the IL-6 receptor has been shown to reduce pro-BNP and improve LV-function in RA patients without previously known HF." (PMID 35548445, 2022). "Mechanistically, these expanded inflammatory Thy1+ fibroblasts were shown to drive inflammation in rheumatoid arthritis by secreting IL6 and chemokines such as CCL2, CX3CL1, CXCL9, and CXCL12." (PMID 35085231, 2022). "The role of IL-6 in the diminished CYP3A-mediated clearance of drugs in rheumatoid arthritis has been documented in clinical trials of monoclonal antibodies targeting IL-6." (PMID 36359206, 2022). "Her past medical history included hypertension, primary biliary cirrhosis, and rheumatoid arthritis (RA), treated with a steroid agent and interleukin-6 (IL-6) inhibitor." (PMID 35389108, 2022). "In this model of rheumatoid arthritis, the fibroblast secretion of IL-6, CXCL12, and CCL2 in the synovial microenvironment, as well as the expression of an IFN-γ gene signature, stimulates the macrophage-mediated inflammatory response." (PMID 36559029, 2022). "Similar to the targeting of IL-6, anti-TNFα mAbs are used to treat inflammatory conditions, such as rheumatoid arthritis, juvenile arthritis, inflammatory bowel diseases, and psoriasis (reviewed in Refs." (PMID 35890077, 2022). "This indicates that L. casei can inhibit the activation of the pentose phosphate pathway, maintain redox balance, and reduce the production of pro-inflammatory factors IL-1β, IL-6, and IL-17, thereby alleviating rheumatoid arthritis in rats." (PMID 36217542, 2022). "In another study, the blockage of IL-6 by specific humanized neutralizing antibodies was clinically used for patients with rheumatoid arthritis or inflammatory bowel disease with promising effects." (PMID 35280304, 2022). "The same protective effect is observed in a murine model of rheumatoid arthritis where a preestablished Schistosoma infection causes a downregulation of the level of anticollagen IgG, IFN-γ, IL-17A, TNF-α, IL-1β, and IL-6 and an upregulation of IL-4." (PMID 35113966, 2022). "The physiopathology of rheumatoid arthritis is heavily influenced by the overexpression of both IL-6 and IL-1 β." (PMID 35804544, 2022). "Pathogenesis mechanisms of SJIA were dysregulation of immune system, and overproduction of inflammatory cytokines [tumor necrosis factor-α (TNF-α), interleukin-1 (IL-1) and interleukin-6 (IL-6)] resembled those found in adult rheumatoid arthritis (RA)." (PMID 35906625, 2022). "IL-6 is critical for hematopoiesis in the liver and good health, and dysregulated IL-6 expression can lead to diseases such as rheumatoid arthritis, osteoporosis, and cirrhosis." (PMID 36613892, 2022). "Any substance that blocks the production of IL-6 and TNF-α causes a significant revolution in the management of rheumatoid arthritis." (PMID 36353479, 2022). "Tocilizumab (Actemra®), developed as an anti-IL-6 mAb by Chugai, was approved for rheumatoid arthritis treatment in 2010 by the US Food and Drug Administration (FDA)." (PMID 35884906, 2022). "Tocilizumab, an interleukin‐6 (IL-6) antagonist approved for rheumatoid arthritis, is of particular importance because it received conditional recommendations by the German S3 and the ERS guidelines." (PMID 35449467, 2022). "Halting IL-6 signaling via the monoclonal antibody sirukumab also reversed IL-6-mediated suppression of CYP3A, CYP2C9, and CYP2C19 activity in rheumatoid arthritis patients, suggesting that IL-6 is an important regulator of CYP enzymes." (PMID 35185562, 2022). "IL-6 is involved in many biological processes, such as inflammation and immune regulation, while the imbalance of immune regulation of the IL-6/ IL-6 receptor axis can lead to various inflammatory diseases, such as rheumatoid arthritis and chronic hepatitis." (PMID 35744838, 2022).
rheumatoid arthritis (continued). "The IL-6 blockers have been shown as highly effective on the anemia of chronic disease, commonly observed in rheumatoid arthritis (RA)." (PMID 35299233, 2022). "Other disadvantages include the fact that hereditary AIDs can be more difficult to treat than inflammatory diseases such as rheumatoid arthritis, and there are safety and medical-economic issues with the long-term administration of IL-6 inhibitors." (PMID 35958618, 2022). "S100A8/ S100A9 is the most abundant protein in rheumatoid arthritis synovial fluid (SF) and has a key role in promoting IL-6 expression in fibroblast-like synoviocytes (FLS)." (PMID 36700196, 2022). "Interestingly, IL-6 also looks to be implicated in both rheumatoid arthritis (RA) and dermatomyositis, which is an inflammatory muscle disease that involves rashes to the skin." (PMID 36078455, 2022). "Since pro- and anti-inflammatory cytokines play a key role in the pathogenesis and evolution of the inflammatory state of rheumatoid arthritis, three typical markers of rheumatoid arthritis were monitored: IL-1β, IL-6, and TNF-α." (PMID 36421448, 2022). "A study showed that an imbalance in IL-6 cytokine signaling contributes to the onset and maintenance of several diseases, including rheumatoid arthritis and osteoporosis." (PMID 35646835, 2022). "On the other hand, peripheral mononuclear cells from patients with rheumatoid arthritis and cultured in the presence of vitamin D had reduced levels of IL-17, IL-6, and TNF-α." (PMID 35625788, 2022). "Rheumatoid arthritis treatment with neutral electrolyzed saline reduces the joint's mechanical and inflammatory damage, which is correlated with a reduction in IL-6 serum levels." (PMID 35692576, 2022). "Another investigation postulated a relation between increased miR-125b and elevated interleukin-6 (IL-6) in patients diagnosed with rheumatoid arthritis." (PMID 35872885, 2022). "Activation of MAPK members was increased in macrophages and fibroblasts in the synovial tissue of patients with rheumatoid arthritis, which coincided with increased IL-6, TNF-α, and IL-1 stimulation in synovial fibroblast cells." (PMID 35755835, 2022). "Secretion of IL6 and IL10 by differentiated macrophages has been described in immunosuppressive tumor-associated -macrophages, rheumatoid arthritis, asthma and regulating epithelial integrity in the small intestine." (PMID 36561744, 2022). "For example, IL-17A and IL-22 are believed to act in concert in autoimmune pathogenesis and IL-17 has been shown to act synergistically with TNF-α, in the induction of IL-6 in rheumatoid arthritis." (PMID 34203644, 2021). "It has been reported that hyperacetylation of histone H3 in the IL-6 promoter triggers the increase of IL-6 production by rheumatoid arthritis synovial fibroblasts (RASFs)." (PMID 33915757, 2021). "Scholars from Dalian Medical University found that IL-34 increases the expression of IL-6 and then upregulates Th17 to participate in the course of rheumatoid arthritis." (PMID 34095310, 2021). "Administering recombinant IL-1 receptor antagonist or monoclonal antibodies against TNF-α or IL-6 or their receptors has proved beneficial in clinical therapy of patients with rheumatoid arthritis." (PMID 34445536, 2021). "Impaired regulation of IL-6 can lead to immune-related diseases including rheumatoid arthritis, where increased IL-6 levels were observed, and has thus been used as a therapeutic target." (PMID 33925531, 2021). "IL-6 concentrations are raised in a number of systemic inflammatory conditions including rheumatoid arthritis (RA)." (PMID 34813621, 2021). "Meanwhile, IL-6 is also considered as a key inflammatory mediator in the pathogenesis of rheumatoid arthritis." (PMID 34950033, 2021). "One such drug, sarilumab has been shown toinhibit IL-6 mediated signaling and is approved for rheumatoid arthritis." (PMID 34552755, 2021).
rheumatoid arthritis (continued). "Strategies that target IL-6 and its signaling lead to effective prevention and treatment of chronic inflammatory diseases, such as rheumatoid arthritis." (PMID 34822503, 2021). "Elevated serum levels of IL-6 are found in many inflammatory diseases, and the blockade of IL-6 signaling with antibodies targeting either IL-6 or the IL-6R is used successfully in the clinic, e.g., for patients with rheumatoid arthritis." (PMID 34281231, 2021). "Our findings demonstrated that SJT strongly alleviated rheumatoid arthritis and reduced the secretion of IL-6, IL-1β, TNF-α of AIA rats." (PMID 34393779, 2021). "Scolopendrasin IX, another peptide isolated from the same centipede species, can down-regulate the expression of pro-inflammatory mediators such as TNF-α and IL-6, also having therapeutic effects against rheumatoid arthritis." (PMID 34795699, 2021). "Anti-IL-6 therapy has been met with success in the treatment of rheumatoid arthritis, and mice treated with anti-IL6 and/or anti-IL-6R antibody therapy markedly reduces post-traumatic OA, laying the foundation for its use as a therapy to treat OA." (PMID 36474817, 2021). "Conversely, IL-6 trans-signalling, which has been implicated in chronic inflammatory conditions such as rheumatoid arthritis and is primarily responsible for the pro-inflammatory role of IL-6, may be responsible for risk-increasing associations of genetic instruments for IL-6." (PMID 34135474, 2021). "Interleukin-6 (IL-6), a pleiotropic cytokine that regulates immune responses and inflammatory reactions, plays a pivotal role in the development of rheumatoid arthritis (RA)." (PMID 35126375, 2021). "Tocilizumab is another anti-IL-6 monoclonalantibody agent approved by the FDA for rheumatoid arthritis." (PMID 34552755, 2021). "Supporting this, the levels of inflammatory factors such as IL-6 (the marker of rheumatoid arthritis) display diurnal oscillations with a peak level in the morning." (PMID 34108880, 2021). "Oncostatin M (OSM) is a cytokine from the interleukin 6 (IL-6) family that has been shown to be elevated in synovial fluid of most rheumatoid arthritis (RA) patients, but only in a limited subset of OA patients." (PMID 33673583, 2021). "Anticytokine therapy includes Tocilizumab (TCZ) which has been used worldwide.Tocilizumab is one of the first interleukin-6(IL-6) blocking antibodies and has proved its safety and effectiveness in therapy for rheumatoid arthritis." (PMID 33585031, 2021). "Increased or dysregulated IL-6 trans-signaling contributes to the development of many chronic inflammatory diseases including rheumatoid arthritis, multiple sclerosis, inflammatory bowel disease, and cancer." (PMID 34927050, 2021). "Rheumatoid arthritis synovial fibroblasts (RASFs) contribute to synovial inflammation and bone destruction by producing a pleiotropic cytokine interleukin-6 (IL-6)." (PMID 34795667, 2021). "In this respect, it is worth to remind that tocilizumab is currently used to treat rheumatoid arthritis, where the antibody is expected to reduce IL6 inflammatory activity affecting articular cartilage." (PMID 33393189, 2021). "Meanwhile, elevated TNF-α and IL-6 stimulate the expression of rheumatoid arthritis-related proteins such as C-reactive protein." (PMID 34108880, 2021). "The major green tea catechin, epigallocatechin-3-O-gallate (EGCG), has attracted significant interest for rheumatoid arthritis therapy because of its ability to suppress the proliferation and interleukin-6 secretion of synoviocytes." (PMID 35423998, 2021). "Anti-IL6 drugs tocilizumab and sarilumab are known to be very effective in the treatment of rheumatoid arthritis, juvenile idiopathic arthritis, systemic, giant cell arteritis, and Cytokine Release Syndrome which occurs during therapy with Car-T." (PMID 33429732, 2021).
rheumatoid arthritis (continued). "TNF-α, IL-1β, and IL-6 have been well documented for their role in several inflammatory conditions, including lung inflammation, rheumatoid arthritis, and intestinal bowel diseases (IBD)." (PMID 34940701, 2021). "IL-6 is one of the main cytokines in the expression of persistence and exacerbation inflammatory and autoimmune diseases such as rheumatoid arthritis, systemic sclerosis, asthma, and other diseases." (PMID 34830006, 2021). "Of note, IL-6 is also involved in a plethora of other biological processes such as inflammation, ageing, autoimmune (rheumatoid arthritis) and psychiatric disorders (bipolar disorder and anorexia)." (PMID 34681685, 2021). "IL-6 participates in the pathogenesis of several inflammatory diseases, and inhibitors of IL-6 are commonly used to treat rheumatoid arthritis and other classical inflammatory diseases such as Crohn’s disease and psoriasis." (PMID 33897686, 2021). "Excessively high levels of IL-6 have been detected in several diseases, most commonly in rheumatoid arthritis (RA) and Castleman's disease, as well as in a variety of tumors." (PMID 34692846, 2021). "There is evidence that IL-6 blockade strategy is beneficial for several inflammatory diseases, such as rheumatoid arthritis, juvenile idiopathic arthritis." (PMID 34327146, 2021). "DILC has an appreciated role in the pathogenesis a the immune-mediated disorder rheumatoid arthritis through modulating IL-6 expression." (PMID 34658787, 2021). "Previous studies have documented the role of IL-6 and IL-1β deregulation in the pathogenesis of systemic-onset juvenile chronic arthritis, rheumatoid arthritis and psoriasis." (PMID 33743681, 2021). "TQ treatment was previously shown to inhibit TNF-α and IL-6 production to limit inflammation in rheumatoid arthritis synovial fibroblasts." (PMID 33920708, 2021). "IL-1 responses contribute to protection against Mtb challenge in mouse models, but exaggerated IL-1 and IL-6 responses promote immunopathology in other chronic inflammatory conditions, such as juvenile idiopathic arthritis and rheumatoid arthritis." (PMID 33952677, 2021). "To date, inhibition of IL-6 signaling antibodies directed against IL-6 and the IL-6R have been approved for e.g. rheumatoid arthritis." (PMID 34927050, 2021). "Several studies have demonstrated that various immune mediators are also implicated, including macrophage inhibitory factor (MIF), an important cytokine in the pathogenesis of rheumatoid arthritis, and interleukin-6 (IL-6)." (PMID 33711991, 2021). "Since IL-6 is primary mediator in pathogenesis of rheumatoid arthritis; this common pathogenetic link explains the usefulness of EULAR-CSA score in hypothyroidism." (PMID 33592022, 2021). "Interleukin (IL)-6 trans-signaling is of particular importance because it drives the development of autoimmune diseases, including rheumatoid arthritis and chronic inflammatory bowel diseases, whereas a role for IL-11 trans-signaling remains elusive." (PMID 34927050, 2021). "Taking these findings into account, it is most likely that HSP22 affects the IL-6 production in osteoblast and the development of rheumatoid arthritis." (PMID 33478532, 2021). "IL-6 and TNF-α are proinflammatory cytokines whose elevations have been associated with pathologies of rheumatoid arthritis." (PMID 34108880, 2021). "NSAID was found to reduce IL-6 in the synovial fluid of rheumatoid arthritis patients, and in the sputum of cystic fibrosis patients." (PMID 33995033, 2021). "In the late phase of rheumatoid arthritis, HGF promoted synovitis by activating fibroblast-like synoviocytes to produce pathogenic IL-6, which accelerated cell proliferation and induced apoptosis resistance." (PMID 33933140, 2021). "Circulating resistin has been positively correlated with C-reactive protein (CRP), TNF-α, and IL-6 in type 2 diabetes, rheumatoid arthritis, chronic kidney disease, sepsis, and coronary atherosclerosis." (PMID 34639186, 2021).